CRP (C-reactive protein)
Diseases named in the same sentence as CRP in open-access papers (continued):
Sharing a sentence is not in itself a finding about the gene and the disease.
Insulin resistance (continued). "This has been confirmed by the analysis of the relationship between high levels of C-reactive protein (CRP) (a sensitive marker of subclinical inflammation) and insulin resistance, as well as the components of Mets." (PMID 32751810, 2020). "The role of insulin resistance and low-grade chronic inflammation (CRP) in initiating lung abnormalities deserves more attention." (PMID 33148273, 2020). "The Camellia sinensis teas prevented LVH, and partially prevented insulin resistance and increased levels of CRP." (PMID 32348424, 2020). "Besides, deteriorated metabolic status influences elevated levels of inflammatory cytokines such as interleukin 6 (IL-6), tumor necrosis factor alpha (TNF-α), C-reactive protein (CRP), and leptin hormone, which may be implicated in insulin resistance and tumor development." (PMID 33238496, 2020). "Insulin resistance and AN are partial mediators of BMI with genetic and environmental sharing influences on CRP, blood pressure, lipids, and physical fitness." (PMID 33057385, 2020). "The multivariate model selected measures of central obesity, atherogenic dyslipidemia, insulin resistance, and uric acid as significant predictors of BP in both genders, and C-reactive protein in females." (PMID 32455627, 2020). "In our systematic review, we assumed that obese patients receiving whole grain diet intervention would have lower CVD risk factors, such as body weight, LDL-C concentration, SBP, waist circumference, CRP, insulin resistance index and BMI." (PMID 32070285, 2020). "Low-grade systemic inflammation has been independently implicated in metabolic disorders, such as insulin resistance and T2DM, and is typically presented with elevated levels of pro-inflammatory cytokines (i.e. IL-6, TNF-α, and CRP)." (PMID 33028418, 2020). "It has been reported that inflammatory markers such as CRP, fibrinogen, and IL-6 increase in insulin resistance." (PMID 32907593, 2020). "Supplementation with vitamin D in obese adolescents resulted in decrease of insulin resistance, while levels of inflammatory markers [CRP, TNF–α, IL–6] remained unchanged." (PMID 32326621, 2020). "CRP is a prominent biomarker for insulin resistance and CVD, and SAA antagonizes insulin action in adipocytes, thus contributing to systemic insulin resistance." (PMID 32158768, 2020). "Also, non-adherent participants were associated with higher weight gain, lipid profile, CRP, and insulin resistance as well as poor glycemic control, suggesting possible connections with diet, gut microbiota, energy metabolism, low-grade inflammation, and insulin resistance in women with GDM." (PMID 32500037, 2020). "These inflammatory markers also lead to an acute phase response with increased hepatic production of C-reactive protein (CRP), a sensitive marker of low-grade systemic inflammation which directly promotes insulin resistance." (PMID 33204677, 2020). "Other authors asserted about the strict dependence of the developing insulin resistance in T2DM patients on the increased level of CRP." (PMID 32326243, 2020). "Epidemiological studies have indicated that visceral fat is correlated with insulin resistance (IR) and glucose intolerance and increasing levels of C-reactive protein (CRP), TNF-α, IL-6, isoprostanes and monocyte chemoattractant protein-1 (MCP-1)." (PMID 31907080, 2020). "Increased levels of CRP were found to correlate with metabolic inflammation, insulin resistance, adiposity, atherothrombosis, and other key features of metabolic syndrome." (PMID 31718015, 2019). "To test the relation of inflammatory markers and adipose tissue insulin resistance, we first tested simple correlations of adipose insulin resistance indices and IL-6/CRP." (PMID 30637483, 2019). "Further, C-reactive protein (CRP), a marker of inflammation in T2DM, caused insulin resistance in this same study." (PMID 31921122, 2019).
Insulin resistance (continued). "Elevated levels of pro-inflammatory biomarkers such as TNF-α, interleukin-6 (IL-6) and interleukin-8 (IL-8), and C-reactive protein (CRP) have all been reported in various insulin resistance states." (PMID 29955954, 2019). "M1 macrophages secrete the proinflammatory cytokines TNF-α, IL-1β, and IL-6, which promote insulin resistance and the accompanying deleterious metabolic effects, as well as synthesis of C-reactive protein." (PMID 31015797, 2019). "At the beginning and after eight weeks of follow-up, body composition was evaluated by using dual-energy X-ray absorptiometry and lipid profile, insulin resistance, C-reactive protein, adiponectin, leptin and nesfastin plasma concentrations were analyzed." (PMID 31480676, 2019). "These proinflammatory markers, as well as CRP, are suggested to induce insulin resistance and gluconeogenesis, subsequent hyperglycemia, and attenuate insulin signaling and sensitivity through insulin receptor substrate phosphorylation." (PMID 31143476, 2019). "In the regression analysis, insulin resistance was the most influential determinant of atherosclerosis in psoriasis and C-reactive protein the most significant predictor of insulin resistance." (PMID 30735527, 2019). "We demonstrated both a significant reduction in homeostasis model assessment of insulin resistance index and high-sensitivity CRP levels in the gastric bypass group when compared with controls." (PMID 29133606, 2018). "A significant p for trend was found for CRVE and serum CRP concentration quartiles (p = 0.049), homeostatic model assessment of insulin resistance (HOMA-IR) quartiles (p = 0.040), and serum HbA1c concentration quartiles (p = 0.031)." (PMID 30446681, 2018). "Authors studied 5079 individuals free of CVD (61 ± 10 years) and found that a high quality dietary pattern was associated with less regional adiposity and a lower body mass index (BMI), CRP, and insulin resistance." (PMID 30544955, 2018). "Vascular inflammation evaluated by FDG PET has been positively related to metabolic syndrome components and traditional risk factors of cardiovascular disease, including high-sensitivity C-reactive protein, body mass index, and insulin resistance." (PMID 30274193, 2018). "Adiponectin is the most important factor for increasing insulin sensitivity, while factors including leptin, resistin and C-reactive protein are known to be correlated with the increase of insulin resistance." (PMID 29793496, 2018). "We have shown that the total body fat mass and subcutaneous abdominal fat are associated with insulin resistance in women with a history of GDM and now add that increased CRP is related to reduced insulin sensitivity." (PMID 29951553, 2018). "Prior studies in PLHIV in the US and Europe have linked soluble inflammatory mediators (e.g., C-reactive protein (CRP) and interleukin-6 (IL-6)) to insulin resistance or incident DM." (PMID 30009182, 2018). "Low-grade systemic inflammation as measured by serum concentrations of CRP is related to insulin resistance and ASCVD." (PMID 29452596, 2018). "Shift workers exposed to irregular sleep schedules resulting in sleep deprivation and misalignment of circadian rhythms, have increased CRP levels and insulin resistance." (PMID 30402295, 2018). "ABPM: ambulatory blood pressure monitoring; DAP: diastolic arterial pressure; HOMA-IR: homeostatic model assessment of insulin resistance; hs-CRP: high-sensitivity C-reactive protein; MAP, mean arterial pressure; SAP: systolic arterial pressure." (PMID 29340522, 2018). "A fasting blood sample was used for measurement of insulin, glucose (from which homeostasis model assessment [HOMA]‐insulin resistance [IR] was derived), glycated hemoglobin (HbA1c), urate, C‐reactive protein (CRP), and lipids." (PMID 29411507, 2018).
Insulin resistance (continued). "An animal study using rats provided in vivo evidence that human CRP plays an active role in inducing hepatic insulin resistance, which is at least partially achieved through impairment in the insulin signaling pathway." (PMID 28575103, 2017). "There is strong evidence that a persistent inflammatory state, as occurs in hemodialysis patients, interferes with normal insulin signaling and inflammatory markers as interleukin 6 and C-reactive protein correlated with insulin resistance in clinical trials." (PMID 28719612, 2017). "The macrophages in adipose cells secrete proinflammatory cytokines (adipocytokines) such as C-reactive protein, interleukin (IL)–6, IL-8, IL-10, and tumor necrosis factor–α; these cytokines impair insulin signaling, inducing insulin resistance." (PMID 28234943, 2017). "The patients classified as being insulin-resistant had higher inflammatory markers (CRP, TNF-alpha, and IL-6) and higher disease activity: mean DAS28 score in the non-IR group was 3.6, and in the IR group it was 4.6." (PMID 28932748, 2017). "Pregnancy is also associated with a transient worsening of the cardiovascular risk profile including increases in dyslipidaemia, insulin resistance, oxidative stress, cytokines such as IL-6 and TNF-α, and inflammatory markers such as CRP." (PMID 28193219, 2017). "Elevated levels of IL-6 and CRP levels among individuals with features of the insulin resistance and type 2 diabetes have been apparent." (PMID 28555043, 2017). "For instance, CRP and pro-inflammatory cytokines, activated by increased cortisol, affect insulin resistance and dyslipidemia." (PMID 29125555, 2017). "A significant difference in BMI, waist-to-hip ratio, smoking status, high-sensitivity C-reactive protein (hS-CRP), insulin resistance (HOMA-IR), number of diseased coronary arteries and Gensini score was found between different glucose metabolism categories." (PMID 28854264, 2017). "Plasma IL-6, CRP, glucose, serum insulin, and homeostasis model assessment of insulin resistance were significantly greater in OO compared with OL and YL (P < 0.01)." (PMID 28911148, 2017). "Human CRP plays an active role in inducing hepatic insulin resistance in rats, partially by activating extracellular signal-regulated kinase (ERK), with downstream impairment in the insulin signaling pathway." (PMID 28361994, 2017). "CRP, IL-6, IL-18 and TNF-α have been related to the risk of developing type 2 diabetes and cardiovascular diseases that are strongly associated with insulin resistance and body fat amount." (PMID 29201665, 2017). "Briefly, BMI, systolic BP, CRP and estimated insulin resistance was consistently positively-, while estimated insulin sensitivity and β-cell function were consistently negatively, associated with the L/A ratio at each visit in univariate analysis." (PMID 28068986, 2017). "It was found that salsalate ameliorates insulin resistance and dyslipidaemia by reducing inflammation induced by the human CRP transgene and by activating brown adipose tissue (BAT)." (PMID 28586387, 2017). "Increased level of IL-6, TNF-α and CRP are thought to contribute to the development of insulin resistance, T2DM, and CVD." (PMID 28125601, 2017). "There is a positive correlation between CRP concentration and insulin resistance and elevated levels of CRP have been reported in GDM." (PMID 28699987, 2017). "Many studies have confirmed that in women with PCOS, a positive relationship exists among CRP values and insulin resistance, body weight and fatty mass." (PMID 29201665, 2017). "This study aimed to evaluatethe therapeutic effects of curcumin on IL-6 and CRP levels as well as insulin resistance(IR) index on liver function in PCOS rats." (PMID 28836404, 2017). "This association was observed regardless of abdominal obesity or body fat percentage, and was only modestly explained by insulin resistance or chronic inflammation, as represented by CRP levels." (PMID 28400989, 2017).
Insulin resistance (continued). "The higher level of proinflammatory cytokines and plasma CRP thus indicates the likelihood of insulin resistance in our GDM model." (PMID 27379252, 2016). "CRP is the most important inflammation biomarker in humans; it is elevated in status of systemic inflammation and is also related to insulin resistance and metabolic syndrome." (PMID 27409634, 2016). "The women in the raised inflammatory status also had higher BMI and insulin resistance, as well as fibrinogen and CRP." (PMID 27258299, 2016). "Model 2 shows that presence of insulin resistance was positively associated with MCP-1 (OR = 1.005, p = 0.024) and IL-6 levels; and, negatively associated with CRP levels (OR = 0.989, p = 0.049)." (PMID 26862350, 2016). "In the present study, the overweight group showed glucose, insulin, HOMA-IR, and hs-CRP than control group, indicating insulin resistance and increased inflammatory status than controls." (PMID 25781947, 2015). "10- and 12-(Z,E)-HODE/LA, RBP4, hs-CRP, and adiponectin were significantly correlated with both glucose tolerance and insulin resistance." (PMID 26132231, 2015). "Linear regression models examined each eating frequency and timing exposure variable with C-reactive protein (CRP) concentrations and the Homeostatic Model Assessment of Insulin Resistance (HOMA-IR)." (PMID 26305095, 2015). "No significant intervention effect was observed for adiponectin, insulin resistance, or inflammatory markers (CRP, IL-6 and TNF-a) although the findings were inconclusive." (PMID 25706622, 2015). "We found that higher levels of CRP, as well as of PAI-1 and TNFα, were independently associated with both insulin resistance and microvascular dysfunction (lower capillary density)." (PMID 26549941, 2015). "High fructose diet increased lipogenesis, leptin resistance, intra-abdominal fat storage, hunger rating, energy intake, CRP concentration, blood pressure, and induced impaired fasting glucose by insulin resistance in the liver and adipose tissue." (PMID 26225136, 2015). "Models* of associations of Eating Patterns and Lifestyle Factors with C-Reactive Protein (CRP) and Homeostatic Model Assessment of Insulin Resistance (HOMA-IR) in Adult Women Participants From the NHANES 2009–2010 Survey Year." (PMID 26305095, 2015). "Although metabolic parameters in the offspring cohorts were not statistically significantly different owing to sample size, the differences were clinically significant particularly for insulin resistance, dyslipidemia and CRP." (PMID 25603303, 2015). "CRP has also been previously correlated with both insulin resistance and endothelial dysfunction in healthy adults, but the average age of subjects in that study was 59 years, in contrast to 27 years in our study." (PMID 26549941, 2015). "Correspondingly, TNF-α concentration correlated with the degree of stunting in girls, and IL-6, CRP and insulin resistance correlated with the degree of stunting and adiposity in boys in South Africa." (PMID 26445018, 2015). "Biomarkers of MetS are insulin resistance, leptin, and changes in epinephrine and norepinephrine, oxidized low-density lipoprotein cholesterol, uric acid, C-reactive protein (CRP), plasminogen activator inhibitor-1, and aldosterone." (PMID 25853137, 2015). "Increased levels of acute phase proteins such as C-reactive protein (CRP), interleukin 6 (IL6) and sialic acid have been shown in patients with T2DM and insulin resistance and are known to be associated with CVD." (PMID 24955136, 2014). "We applied Wildman (W), Wildman modified (WM) with insulin resistance (IR) with cut-off point ≥3.8 and levels of C- Reactive Protein (CRP) ≥3 mg/l; and Consensus Societies (CS) criteria." (PMID 25198070, 2014). "Several insulin resistance indices, inflammatory cytokines or adipokines, including C-reactive protein, adiponectin, and tumor necrosis factor-α, were all improved in both groups." (PMID 26137510, 2014).
Insulin resistance (continued). "In conclusion, circulating fractalkine predicts the development of the MetS independently of central obesity, CRP, insulin resistance, and dyslipidemia." (PMID 24883062, 2014). "On the other hand, previous studies have demonstrated a significant correlation between CRP levels and features of the metabolic syndrome, including adiposity, hyperinsulinemia, insulin resistance, hypertriglyceridemia and low HDLc." (PMID 24495560, 2014). "Some studies have demonstrated significant correlation between CRP levels with features of the metabolic syndrome, including adiposity, hyperinsulinemia, insulin resistance, hypertriglyceridemia and low HDLc." (PMID 24495560, 2014). "The two groups were well matched for BMI and circulating levels of biomarkers involved in glycaemic control, indices of insulin resistance, inflammation (IL-6, CRP, TNF-α, MIF), oxidative stress and SpO2." (PMID 24733551, 2014). "Descriptive statistics for C-reactive protein (CRP), insulin resistance (HOMA-IR) and waist circumference." (PMID 24681553, 2014). "It is known that TNF-alpha, IL-6, and CRP play an important role in insulin resistance and the vascular inflammation process through their multiple actions." (PMID 24249586, 2014). "Insulin resistance was also assessed, as well as a large number of biomarkers including high sensitivity C-reactive protein (hS-CRP)." (PMID 24681553, 2014). "Significant differences were found in levels of LDL-L, total cholesterol, CRP, peripheral blood lymphocyte counts, and the logarithmical values of homeostasis model assessment of insulin resistance (Ln(HOMA-IR))." (PMID 24803740, 2014). "Several studies in healthy subjects have confirmed that elevated levels of CRP and cytokines IL-6 and TNF-alpha are associated with insulin resistance." (PMID 23690772, 2013). "Previous studies have shown that SAD is a predictor of insulin resistance and levels of CRP in immigrant women from the middle-east as well as in obese men and that SAD is closely related to visceral adiposity." (PMID 23536999, 2013). "Other factors in circulation that adversely contribute towards CVD include insulin resistance-induced high glucose and CRP." (PMID 23383064, 2013). "Other studies have demonstrated significant correlation between CRP levels with features of the metabolic syndrome, including adiposity, hyperinsulinemia, insulin resistance, hypertriglyceridemia, and low HDL cholesterol." (PMID 23690772, 2013). "Body fat composition, serum high-sensitivity C-reactive protein (hs-CRP) level and insulin resistance (HOMA-IR) were also assessed." (PMID 24499326, 2013). "Even in these younger women, body fat levels were associated with physiological indices of risk for T2D and cardiovascular disease, such as LDL cholesterol, CRP, blood pressure and insulin resistance (HOMA IR and fasting insulin), as well as WHR." (PMID 24376410, 2013). "As previously reported, compared to white European children, South Asian children had higher sum of skinfolds, fat mass index, HbA1c, glucose, insulin resistance, triglycerides and C-reactive protein and lower HDL-cholesterol." (PMID 22412897, 2012). "Although the predictive role of hs-CRP for insulin resistance and/or MetS had been disclosed in Han Chinese and Japanese populations, but no statistical significance in the current study." (PMID 22719971, 2012). "Black African-Caribbean children had less marked increases in HbA1c, insulin resistance and C-reactive protein, but conversely, had lower triglycerides and higher HDL-cholesterol; adiposity levels were not consistently increased." (PMID 22412897, 2012). "Over time, insulin resistance leads to increased levels of pro-inflammatory cytokines like CRP and homocysteine that accelerate atherogenesis, plaque rupture, and MACE." (PMID 23270513, 2012).